GRPR (gastrin releasing peptide receptor)
Diseases named in the same sentence as GRPR in open-access papers (continued):
Sharing a sentence is not in itself a finding about the gene and the disease.
cancer (continued). "In contrast, in the current study bronchial GRPR expression was detected in only a minority of cancer-free controls who were former smokers." (PMID 22296774, 2012). "Both membranous and cytoplasmic expression of GRPR was detected in ER-positive cancer cells." (PMID 40871022, 2025). "The ability to target either GRPR or αvβ3 biomarkers simultaneously via a heterodimeric targeting ligand has provided a new avenue to investigate the dual targeting capacity of bivalent radioligands for improved in vivo PET images of specific human cancers." (PMID 40430268, 2025). "GRPR is known to be overexpressed in many types of cancer under normoxic conditions." (PMID 41226822, 2025). "The involvement of GRPR in itch and nociception offers potential cancer and pain therapy." (PMID 40500450, 2025). "This is in line with all previous data, which corroborate the evidence that UniCAR T-cells undergo activation, release of pro-inflammatory cytokines, and killing of GRPR-expressing cancer cells exclusively in the presence of target cells and the respective BBN2 TMs." (PMID 40141329, 2025). "The gastrin releasing peptide receptor (GRPR) still keeps attracting the spotlight as a valid biomolecular target for the development of novel radiopharmaceuticals for personalized management of a wide range of cancer patients." (PMID 40745236, 2025). "We report the microwave-assisted synthesis of a novelfamily ofpeptide-linked optical imaging probes incorporating the L- bombesin fragment (denoted L- ­BBN)as a functional building block currently used for targeting the gastrin-releasingpeptide receptor (GRPR) in cancer cells." (PMID 41425801, 2025). "GRPR is a very promising target for cancer diagnosis and therapy." (PMID 40283887, 2025). "Of particular interest is the gastrin-releasing peptide receptor (GRPR), which has been attracting considerable attention in the nuclear medicine community, owing to its high-density expression in a multitude of frequently occurring malignant tumors." (PMID 41155959, 2025). "GRPR is a G-protein from the bombesin receptor family which is significantly overexpressed in the majority of prostate cancer cases (62–100%) but also in other cancers (breast, lung, head and neck, pancreatic) and brain malignant tumors." (PMID 41300900, 2025). "GRP induces signalling through its receptor (GRPR), a G protein–coupled receptor (GPCR) that has been implicated in promoting cell proliferation, metastasis, and survival in several cancers such as those originating from the prostate, breast, pancreas and lung." (PMID 41226822, 2025). "Therefore, the goal of this study was to evaluate the potential of C-terminal hydroxamate-derived GRPR-targeted radioligands for cancer imaging, and document the extent of their uptake in the pancreas." (PMID 38999054, 2024). "Thus, this peptide sequence has been used for the design of GRPR-targeted radiopharmaceuticals for cancer diagnosis and radioligand therapy." (PMID 38794191, 2024). "We also evaluated the effects of GRPR inhibition on cancer cell invasion and proliferation." (PMID 39768218, 2024). "Thus, GRPR is considered a promising target for the design of targeted radiopharmaceuticals for the diagnosis and radioligand therapy of GRPR-expressing cancers." (PMID 38794191, 2024). "This makes GRPR an appealing target for cancer therapy and diagnosis." (PMID 39768218, 2024). "Importantly, suppression of CRABP2 or FNDC4 reduced cancer invasion, even in the presence of GRPR overexpression, suggesting that these genes play a critical role in LUAD metastasis." (PMID 39768218, 2024). "Due to its expression pattern, GRPR is an attractive target for cancer imaging and therapy." (PMID 39598465, 2024). "Furthermore, high expression of GRPR has been observed in several other types of cancer, although further details on these findings are beyond the scope of this discussion." (PMID 38279185, 2024).
cancer (continued). "Inhibiting GRPR signaling has been shown to reduce cancer cell growth and viability." (PMID 39768218, 2024). "In addition, multiple studies have shown that radiolabeled GRPR antagonists are better than agonists for cancer therapy." (PMID 38195680, 2024). "Both lipidated and non-lipidated bombesin peptides were conjugated to the thiol-tubugi payloads and the resulting conjugates were evaluated for their anti-proliferative activity in a variety of cancer cells expressing GRPR (bombesin receptor) at different levels." (PMID 39600359, 2024). "Notably, genes promoting metastasis in various cancer types were significantly enriched in the GRPR-overexpressing cells (FDR < 0.25)." (PMID 39768218, 2024). "In addition to somatostatin and integrin receptors, other peptide-binding receptors that have been targeted in cancer therapy include the folate receptor, the gastrin-releasing peptide receptor, and the epidermal growth factor receptor." (PMID 38961887, 2024). "Folate is essential for the fast metabolism of cancer cells because of its pivotal role in DNA synthesis and repair; therefore, the concomitant target of FR and GRPR is expected to improve both the BC cells recognition and the theranostic properties of the tracer." (PMID 38020178, 2023). "The significant correlation between GRPR and ER expression has been demonstrated in previous studies conducted in both BC and PC, suggesting a potential important role of ER in mediating GRPR expression and contributing to cancer development, nevertheless this still requires further investigations." (PMID 38020178, 2023). "Gastrin-releasing peptide receptor (GRPR) is overexpressed on the surface of different cancers." (PMID 37298101, 2023). "The overexpression of GRPR in malignant tissues makes it a promising target for the design of targeted radiopharmaceuticals for the diagnosis and radioligand therapy of GRPR-expressing cancer." (PMID 36838968, 2023). "It should be noted that these GRPR-agonist-based radiopeptides typically display high internalization rates in cancer cell lines, such as in human androgen-independent prostate adenocarcinoma PC-3 cells or human breast T-47D cells broadly used as GRPR-positive cell models." (PMID 37242457, 2023). "Researchers dealing with targeted nanomedicines and nuclear sciences have developed various strategies to exploit the potential of GRPR targeting with nanoformulations aiming at either cancer treatment, imaging, and diagnosis, or the combination of those two modalities." (PMID 36834867, 2023). "[64Cu]Cu-SAR-BBN is in clinical development for PET imaging of GRPR-expressing cancers." (PMID 35745647, 2022). "GRPR is coupled with phospholipase C, followed by protein kinase C (PKC) activation, which regulates cell cycle, cell proliferation, and is implicated in the development of malignant neoplasms." (PMID 35744904, 2022). "The GRPR, in particular, has attracted much attention in oncology and in nuclear medicine by virtue of its high-density expression in major human cancers, such as prostate, breast, and small-cell lung cancer, as well as in gastrinoma, gastrointestinal stromal tumors, and other cancer types." (PMID 34830920, 2021). "Over recent decades, GRPR has been found to be highly expressed in various human cancers such as lung, gastric, breast, pancreas, prostate, colorectal, ovarian, and endometrial cancers, and gliomas, but it has a low expression or no expression in normal tissues." (PMID 34771622, 2021). "Radiolabeled GRPR antagonists have shown superior value to the agonists in terms of better pharmacokinetic properties, very good in vivo stability and, by that, sufficient retention in cancer cells." (PMID 33669938, 2021). "Consequently, another paradigm was urgently needed for theranostic management of GRPR-positive cancers with this issue being promptly addressed by the advent of radiolabeled GRPR antagonists (vide infra)." (PMID 34830920, 2021).
cancer (continued). "Clinical testing of three main major antagonist types led to promising outcomes, but at the same time brought to light several limitations of this concept, partly related to the variation of GRPR expression levels across cancer types, stages, previous treatments, and other factors." (PMID 34830920, 2021). "Our incomplete understanding of cancer pathology needs to be improved in order to provide solid information on critical issues, such as GRPR expression status in different types and stages of cancer, as well as following previous therapies in cases of advanced disease." (PMID 34830920, 2021). "This included nanoconstructs decorated with bombesin (BBN) analogues, a bioactive peptide with high affinity towards the Gastrin Releasing Peptide receptor (GRPr) overexpressed in a variety of human cancers, and demonstrated that the AuNPs displayed specificity towards GRPr overexpressing tumors." (PMID 31978954, 2020). "The gastrin-releasing peptide receptor (BB2r) is a G-protein coupled receptor that has been of significant interest to the field of cancer drug development due to its overexpression in a variety of cancers, including prostate cancer." (PMID 31366895, 2019). "The two GRPR and NMBR subtypes are physiologically expressed in the human brain and the gut, especially in stomach, pancreas, and gastrointestinal tract, and they are also implicated in cancer." (PMID 30897789, 2019). "Consequently, they have attracted considerable attention as potential biomolecular targets for diagnosis and therapy with radionuclide carriers directed to GRPR-positive cancer lesions." (PMID 30897789, 2019). "Also, BB agonists have been coupled to paclitaxel, doxorubicin, marine toxins, magainin II, and siRNA to the GRPR resulting in decreased cancer cellular proliferation." (PMID 30008698, 2018). "Therefore GRPR has emerged as an attractive target in PCa, a notoriously difficult cancer to diagnose and stage using conventional imaging techniques." (PMID 29097932, 2017). "Therefore, although the numbers are small, among cancer-free control subjects, the relationship between smoking status and bronchial GRPR expression in the 1997 study is consistent with our current study results." (PMID 22296774, 2012). "We tested for association between GRPR expression in non-cancerous surrogate tissues and smoking status and pack-years of tobacco use stratified by cancer status." (PMID 22296774, 2012). "The presence of the GRPR in particular may be a reflection of the general neuroendocrine phenotype of the cancer cells indicating greater neuropeptide dependence for growth." (PMID 12771999, 2003). "This indicates that E-cadherin may commonly regulate GRPR across cancer types." (PMID 40500450, 2025). "Therefore, the use of anti-GRPR specific antibody and GRPR score could enhance the detection of precursor lesions and cancer and improve the diagnosis, patient management, and monitoring of disease progression." (PMID 40242010, 2025). "Although several GRPR-targeted radiotracers have been evaluated in the clinic, the extraordinarily high pancreas uptake might limit the detection of pancreatic cancer and the metastatic lesions of other cancers in and/or adjacent to the pancreas." (PMID 38794191, 2024). "In vitro and in vivo studies demonstrated that the carborane-functionalized GRPR agonist was highly selective and effective in targeting cancer cells that overexpress GRPR, leading to increased uptake of boron-containing compounds and improved therapeutic efficacy in mouse models of cancer." (PMID 38961887, 2024). "Finally, radiotracer binding to various GRPR-expressing human cancer tissues was investigated." (PMID 37584725, 2023). "However, the cell viability for the mixed system—Ac-Cys-Ahx-Lys-BBN/Ac-Cys-Ahx-Lys-RAF@AuNPs—was comparable to Ac-Cys-Ahx-Lys-RAF@AuNPs, and a notable drop in cell viability was observed (53% and 59%, respectively, in reference to untreated samples) for GRPR-positive cancer cells." (PMID 36834867, 2023).
cancer (continued). "GRPR-targeted cancer imaging efficiency of iron oxide nanoparticles is being investigated to a slightly lower extent than gold nanoparticles, but, considering their clinical success, they still pose a great importance in contemporary cancer management, especially in bioimaging of malignant tumors." (PMID 36834867, 2023). "Thus, the bombesin antagonist peptide [67Cu]Cu-SAR-BBN may be a suitable theranostic approach for treating a variety of GRPR-positive cancers." (PMID 35745647, 2022). "Thus, bombesin peptide antagonists may be ideal for theranostic approaches in visualizing and treating GRPR-positive cancers." (PMID 35745647, 2022). "Furthermore, we performed an expression analysis of all GRK4-family members, GRPR and GRPR down-stream signalling components to elucidate whether the effect of sunitinib on cancer cell migration is based on the GRK5-GRPR signalling cascade." (PMID 31664083, 2019). "Furthermore, we observed that treatment with the multispecific kinase inhibitor sunitinib decreases the cancer cell migration by reducing the GRK5 expression levels resulting in attenuated GRPR signalling, depicting a novel mechanism of action of a well-known drug." (PMID 31664083, 2019). "Second, although the immunohistochemistry of integrin αvβ3 and GRPR expression were conducted in this study, quantification and correlation with tracer uptake was not performed due to the heterogeneous and inhomogeneous expression of cell-surface receptors by cancer cells." (PMID 25849333, 2015). "Gastrin‐releasing peptide receptor (GRPR), a bombesin (BBN) receptor and G‐protein coupled receptor subtype, is overexpressed in several cancer types." (PMID 41555955, 2026). "Previously, our group developed one 68Ga-labeled GRPR antagonist ([68Ga]Ga-TacsBOMB5) and two 68Ga-labeled GRPR agonists ([68Ga]Ga-LW01110 and [68Ga]Ga-LW01142) for detecting GRPR-expressing cancer with positron emission tomography (PET)." (PMID 40283887, 2025). "[212Pb]Pb-DOTAM-GRPR1 is a peptidic radiopharmaceutical targeting the gastrin releasing peptide receptor (GRPr), a GPCR expressed by a range of cancers including prostate, breast, pancreatic, and cervical." (PMID 40591218, 2025). "Lango18 and colleagues similarly observed elevated GRPR mRNA in tumors and adjacent normal mucosa from patients with head and neck SCC (HNSCC) compared with normal mucosa from cancer-free individuals (P < 0.001)." (PMID 41266536, 2025). "Another protein that is upregulated in different cancers, including hormone receptor-positive BCa as well as TNBC, is the gastrin-releasing peptide receptor (GRPR)." (PMID 40647404, 2025). "Competitive displacement assays with LNCaP and PC-3 human cancer cell lines demonstrated high binding affinities for PSMA and GRPR of 9.30 ± 2.32 nM and 3.99 ± 1.8 nM, respectively." (PMID 38708130, 2024). "To date, several radiolabeled GRPR-targeting ligands (i.e., AMBA, RM2, and NeoBOMB1), based on the amphibian GRP analog bombesin, have been introduced into the clinic for cancer diagnosis and radioligand therapy." (PMID 35744904, 2022). "The gastrin-releasing peptide receptor (GRPR), also called bombesin receptor 2 (BB2), is a target for noninvasive PET imaging of various types of cancer." (PMID 34228236, 2021). "It is overexpressed in cancer cells and the GRP production along with GRPR overexpression leads to growth autocrine stimulation." (PMID 33854977, 2021). "In this study, we aimed to develop and perform preclinical evaluation of the GRPR antagonist RM26 conjugated to ABD035 and assess the possibility for using the ligand in GRPR-targeting therapy for cancer treatment." (PMID 33081166, 2020). "An interesting new theranostic option for gastrin-releasing peptide receptor (GRPR) positive cancers, is 68Ga- or 177Lu-labelled NeoBOMB1, a DOTA coupled GRPR antagonist with high GRPR affinity and in vivo stability." (PMID 30823564, 2019).
cancer (continued). "Therefore, the study of radiolabeled GRPR-selective agonists is warranted and may provide an alternative platform for the development of radioligands exhibiting new combinations of biological features particularly suited for cancer theranostics." (PMID 30897789, 2019). "This family of peptide receptors contains gastrin-releasing peptide receptor (GRPR), neuromedin B receptor (NMBR), and bombesin receptor subtype 3 (BRS3), which are overexpressed by a number of cancers, including PDAC." (PMID 29865257, 2018). "Though GRPR is overexpressed in many solid tumors, only one other group has evaluated GRPR, GRP and/or their gene product levels in surrogate tissues of cancer patients to date." (PMID 22296774, 2012). "Bombesin is an amphibian neuropeptide of 14 amino acids that shows a high affinity for the human gastrin-releasing peptide receptor (GRP-r, also known as BB2), which is overexpressed on several types of cancer." (PMID 22214362, 2011). "The bombesin (Bn) receptor family [Gastrin-releasing peptide (GRPR/BB2R) and Neuromedin B receptors (NMBR/BB1R)] are G-protein coupled receptors (GPCR’s) with potent growth effects on normal tissues/numerous cancers, often by transactivating the ErbB receptor-tyrosine kinase (RTK) family." (PMID 41007372, 2025). "GRPR overexpression significantly enhanced cancer cell invasion, although it had no impact on cell proliferation." (PMID 39768218, 2024). "For targeting GRPR, RM-26 (GRPR antagonist) and its dual-targeting radiotracers (RGD-RM26-03, denoted as LNC1015) have showed favorable pharmacokinetics and high clinical feasibility for PET/CT imaging of cancer 120-124." (PMID 38773975, 2024). "It was also tested for FAP and GRPR, which are other emerging targets for RPT in cancer." (PMID 39629134, 2024). "In this study GRPR expression was high in PC-3 cells, which are not just a metastatic line but also androgen-independent and agressive cancer, However, we believe that this is due to the fact that PC-3 cells are neuroendocrine prostate cancer cells." (PMID 38880858, 2024). "They observed high expression of both GRP and GRPR in the majority of cancers (62%), while normal adjacent tissues did not exhibit significant expression." (PMID 38279185, 2024). "PSMA, on the other hand, is highly expressed in androgen-sensitive LNCaP cancer cells, which are negative for GRPr." (PMID 39380961, 2023). "The advent of radiolabeled GRPR-antagonists has enabled the performance of therapy clinical studies, providing hopes for safe and effective PRRT in a broader spectrum of frequently occurring cancers." (PMID 37242457, 2023). "GRPr is highly expressed in androgen-independent PC3 cancer cells, while androgen-sensitive LNCaP cancer cells are GRPR negative." (PMID 39380961, 2023). "Accordingly, higher doses of GRPR antagonists can be safely injected into patients without inducing adverse effects or cancer cell proliferation as well as the undesirable downregulation of GRPR." (PMID 37509170, 2023). "In this context, the groups of Beck-Sickinger88 and Hey-Hawkins89, 90, 91 reported that the combination of carborane and hY1R, GRPR, or GhrR could represent a boron delivery agent in BNCT for the delivery of therapeutic drugs to cancer cells." (PMID 35141397, 2022). "While GRPR antagonists do not activate the receptor upon binding, they can successfully target and be retained in GRPR-expressing cancer lesions while rapidly clearing from a physiological organ in both animal models and humans." (PMID 33809749, 2021). "Yet, the molecular mechanism for the increased uptake and radiosensitizing effects of mTORC1 inhibitor rapamycin to [177Lu]Lu-RM2 in GRPR-positive cancers has not been elucidated and this point warrants further investigation." (PMID 34959437, 2021). "High levels of GRPR expression have been documented in a variety of human cancers, including prostate, breast and lung cancer, as opposed to lack of expression in healthy surrounding tissue." (PMID 30871262, 2019).